SLC26A6 (solute carrier family 26 member 6)
Diseases named in the same sentence as SLC26A6 in open-access papers:
SLC26A6 is named in the same sentence as 42 diseases in open-access papers, as found by Europe PMC text mining. Sharing a sentence is not in itself a finding about the gene and the disease. The quoted sentences say what the papers report.
Hyperoxaluria (14 papers, 2018 to 2026). Increased excretion of oxalates in the urine. "Secondly, the first detailed functional analysis of a disease-causing SLC26A6 mutation detected in the genome of a patient with severe hyperoxaluria and nephrolithiasis has recently been described." (PMID 39949394, 2024). "SLC26A6 null mice developed calcium oxalate nephrolithiasis associated with hyperoxaluria and reduced SLC26A6 mRNA and protein expression was found in obesity-related hyperoxaluric mice." (PMID 32887293, 2020). "Notably, a recent study identified a dominant negative mutation in the human SLC26A6 gene that impairs the transport function and membrane expression of SLC26A6, representing a significant risk factor for inherited forms of hyperoxaluria and nephrolithiasis." (PMID 40318213, 2025). "Therefore, functional defects and mutations in human SLC26A6 may cause hyperoxaluria and kidney stones." (PMID 37342493, 2023). "Therefore, SLC26A6 may be used as one of the therapeutic targets for hyperoxaluria caused by various reasons." (PMID 33553213, 2020). "The calcium-sensing receptor (CaSR) and solute carrier family 26 member 6 (SLC26A6) play key roles in hypercalciuria and hyperoxaluria, respectively." (PMID 41938536, 2026). "Slc26a6‐null mice exhibit defects in intestinal oxalate secretion, resulting in enhanced net absorption of ingested oxalate, hyperoxalemia, hyperoxaluria and a high incidence of kidney stones." (PMID 40318213, 2025). "Both hyperoxaluric and non-hyperoxaluric patients were screened for sequence variations in known and candidate genes implicated in hyperoxaluria (AGXT, GRHPR, HOGA1, SLC26A1, SLC26A6, SLC26A7) by targeted next generation sequencing (tNGS)." (PMID 37270618, 2023). "Slc26a6-/- mice have an increased net absorption of dietary oxalate, leading to hyperoxaluria and calcium oxalate lithiasis, highlighting the role of constitutive SLC26A6 in limiting net intestinal absorption of oxalate." (PMID 37761859, 2023). "Abnormal expression and function of SLC26A6 in the intestine and kidney are closely related to hyperoxalemia, hyperoxaluria, and renal calcium oxalate stones." (PMID 37342493, 2023). "Increased transport of oxalate via SLC26A6 inhibited citrate transport by NaDC‐1 in this cellular model and the hyperoxaluria in the SLC26A6‐/‐ mice is accompanied by hypocitraturia." (PMID 34231328, 2021). "In the past 2 decades, five studies reported that SLC26A6 knockout mice developed renal CaOx stones, hyperkalemia, and hyperoxaluria due to the enhanced net oxalate absorption in the ileum (19, 20, 42, –, 44)." (PMID 34783577, 2021). "Studies have demonstrated that SLC26A6 has fundamental roles not only in proximal tubule NaCl transport but also in the prevention of hyperoxaluria as well as calcium oxalate nephrolithiasis." (PMID 33553213, 2020). "Moreover, SLC26A6 knockout mice were found to develop hyperoxalemia, hyperoxaluria, and calcium oxalate stone formation." (PMID 32887293, 2020). "To evaluate the contribution of genetic factors in the development of hyperoxaluria after bariatric surgery, we conducted tNGS to detect variations within genes known to cause monogenic hyperoxaluria and Ca-Ox-NL (AGXT, GRHPR, HOGA1; SLC26A1) as well as the candidate genes SLC26A6 and SLC26A7." (PMID 37270618, 2023). "This may indicate that a substantial decrease in urinary citrate caused by impaired SLC26A6 regulation of citrate absorption is sufficient to cause stone formation even in the absence of hyperoxaluria." (PMID 32317970, 2020). "Lacking SLC26A6 results in a defect in intestinal Ox secretion, enhanced net absorption of Ox, elevated plasma levels of Ox, and hyperoxaluria." (PMID 35346210, 2022).
kidney stone (14 papers, 2014 to 2026). "Secondly, whole exon sequencing of a kidney stone cohort from the United Kingdom database revealed a dominant negative SLC26A6 mutation in a patient with enteric hyperoxaluria, oxalate kidney stones and a low calcium diet." (PMID 39949394, 2024). "Estrogen activates SLC26A6 in the kidneys, and estrogen-deficient females show lower SLC26A6 activation, with an increase in kidney stones." (PMID 38673775, 2024). "The second study reported the relationship between SLC26A6 gene 206 M polymorphism and the risk of renal calculi in PHPT patients." (PMID 37342493, 2023). "For example, the SLC26A6(V206M) polymorphism, which we also found in our cohort, was shown to be associated with kidney stones development and primary hyperparathyroidism patients." (PMID 32317970, 2020). "Further, mutations in the SLC26A6 gene have been shown in patients with kidney stones." (PMID 40318213, 2025). "Kidney stones are associated with both SLC26A6 and estrogen levels." (PMID 38673775, 2024). "Five studies have reported the effect of SLC26A6 variants on human kidney stones." (PMID 37342493, 2023). "The animal experiment results showed that Slc26a6 was one of the causes of kidney stone formation." (PMID 30002986, 2018). "Estrogen inhibits the generation of kidney stones, and malfunction of SLC26A6 generates kidney stones through systemic reviews and meta-analyses in female patients." (PMID 38673775, 2024). "The future development of bacterial therapy to prevent kidney stones must consider the entire intestinal flora; SLC26A6 is closely related to the excretion of oxalate and is expected to be a target for preventing and treating kidney stones." (PMID 37342493, 2023). "The formation of kidney stones can be prevented by up-regulating or down-regulating SLC26A6 expression." (PMID 37342493, 2023). "When expressed in the intestine, SLC26A6 promotes oxalate excretion, reducing urinary oxalate levels and protecting against kidney stones." (PMID 37881392, 2023). "Jiang and co-workers (2018) reported that patients with recurrent kidney stones have higher expression of SLC26A6 in the kidney and increased renal excretion of oxalate compared to controls, which appears to contribute to the formation of kidney stones." (PMID 37761859, 2023). "SLC26A6 is essential for limiting the net absorption of oxalates by the gut and preventing kidney stones." (PMID 37342493, 2023). "On the other hand, when expressed in the kidney, SLC26A6 increases oxalate excretion, raising urinary oxalate levels and promoting kidney stones." (PMID 37881392, 2023). "SLC26A6 plays a crucial role in preventing and treating kidney stones by regulating oxalate excretion." (PMID 37881392, 2023). "To summarize, the study revealed that having too much SLC26A6 in the kidneys leads to higher oxalate excretion and urinary oxalate concentration, increasing the likelihood of developing kidney stones." (PMID 37881392, 2023). "The high concentration of oxalate in the urine makes the kidney stones appear high frequency in SLC26A6-null mice, and the occurrence rate of male mice is higher than that of female mice." (PMID 33553213, 2020). "SLC26A6 not only participates in the development of intestinal and pancreatic diseases but also serves a significant role in mediating nephrolithiasis, fetal skeletal dysplasia and arrhythmia." (PMID 33553213, 2020). "And nephrolithiasis in the SLC26A6-null mouse is accompanied by 50–75% reduction in intestinal oxalate secretion with increased intestinal oxalate absorption." (PMID 33553213, 2020). "The present case–control study examined the relationship between kidney stones and the role of SLC26A6 in stone formation." (PMID 30002986, 2018). "Western blot and IHC analysis results showed a direct relationship between kidney stone formation and expression of SLC26A6." (PMID 30002986, 2018).
kidney stone (continued). "We genotyped a cohort of 27 Ca2+-oxalate kidney stone formers and 23 healthy non-stone formers, and identified two SLC26A6 polymorphisms located in the region that encodes for the intracellular STAS domain." (PMID 32317970, 2020). "Although a number of studies have shown a close relationship between the expression of SLC26A6 and kidney stone formation, but its precise role in the human diseases remain unknown." (PMID 33553213, 2020). "Numerous studies have demonstrated a close relationship between the expression of SLC26A6 and kidney stone formation, but its exact role in the disease remains unknown." (PMID 30002986, 2018). "The results showed that high expression levels of renal SLC26A6 may account for kidney stone formation." (PMID 30002986, 2018). "Slc26a6-deleted mice showed alterations in epithelial transport functions in the pancreatic ducts, in the proximal intestine, and the salivary glands, without morphological abnormalities, as well as the development of kidney stone on a high oxalate diet, and deficits in pHi-regulation in the heart." (PMID 39949394, 2024). "Hence, the effects of impaired SLC26A6-STAS domain function may extend beyond kidney stone formation and could also lead to hypertension, which is, indeed, strongly associated with kidney stones." (PMID 32317970, 2020). "Interestingly, one compound polymorphism, SLC26A6(D23H/D673N), was found in a kidney stone former, while the other, SLC26A6(R621G), was found in a non-stone former." (PMID 32317970, 2020).
Calcium oxalate nephrolithiasis (5 papers, 2020 to 2026). The presence of calcium- and oxalate-containing calculi (stones) in the kidneys. "This mutation impairs the regulation of NADC-1-mediated citrate transport by weakening the interaction between the STAS domain of SLC26A6 and NADC-1, causing hypocitraturia and occurrence of calcium oxalate kidney stones." (PMID 37342493, 2023). "Similarly, a dominant negative mutation in SLC26A6 and loss-of-function mutations in SLC26A1 are proposed to cause calcium oxalate nephrolithiasis in humans." (PMID 40991662, 2025). "Therefore, elucidating the regulatory mechanism of SLC26A6 is essential for preventing calcium oxalate kidney stones." (PMID 37342493, 2023). "SCFAs can increase the expression of intestinal SLC26A6 and reduce the expression of intestinal SLC26A3, thereby affecting the absorption and excretion of oxalate and reducing the formation of urinary oxalate and calcium oxalate kidney stones." (PMID 37342493, 2023).
Obesity (4 papers, 2017 to 2023). Accumulation of substantial excess body fat. "Moreover, Amin and colleagues (2018) reported that SLC26A6 mRNA and protein levels were decreased in the jejunum of obese ob/ob mice, which is likely mediated by obesity-associated systemic and intestinal inflammation." (PMID 37761859, 2023). "Moreover, obesity-associated cholinergic activity also leads to Slc26a6 inhibition." (PMID 37761859, 2023). "Although little is known about the role of SLC26A6 in the context of obesity, members of the fatty acid transport proteins are widely discussed as regulators of energy homeostasis, exogenous fatty acid uptake, and thermogenesis." (PMID 28831160, 2017).
urolithiasis (4 papers, 2018 to 2025). Stone(s) within the urinary tract. "For instance, mouse SLC26A6 limits urolithiasis, paralleling our results with C. elegans SULP-4." (PMID 40991662, 2025). "Lowering the expression of SLC26A6 in the kidneys could be a promising way to prevent or treat urolithiasis." (PMID 37881392, 2023). "The cellular studies indicate that low Slc26a6 expression levels in the kidney may protect it from urolithiasis formation." (PMID 30405874, 2018). "Downregulating the expression of SLC26A6 in the kidney may be a potential therapeutic target to prevent or treat urolithiasis." (PMID 30002986, 2018). "This study aimed to investigate the role of kidney SLC26A6 in urolithiasis." (PMID 30002986, 2018). "Downregulating the expression of SLC26A6 in the kidneys might be a potential therapeutic target to prevent or treat urolithiasis." (PMID 30002986, 2018).
hepatocellular carcinoma (3 papers, 2023 to 2026). A malignant tumor that arises from hepatocytes. "For example, it was recently shown that SLC26A6 acts as an oncogene in hepatocellular carcinoma and lung cancer." (PMID 38540309, 2024).
type 2 diabetic (3 papers, 2019 to 2021). "Although complicated regulatory mechanisms underlie the various ion transporters, we found enhanced expression of Slc26a6 and Cl− transporting activity in the db/db heart, suggesting that effective Slc26a6 blockers may be efficient in modulating pH of type 2 diabetic hearts." (PMID 31582903, 2019).
adenoma (2 papers, 2018 to 2021). A neoplasm arising from the epithelium. "Two members of the family, SLC26A3 (DRA; downregulated in adenoma) and SLC26A6 (PAT1; putative anion transporter-1), were reported to be expressed in the luminal membrane of pancreatic ducts and function as Cl−–HCO3− exchangers." (PMID 29399744, 2018). "In the mammalian intestine, the two key BBM Cl−/HCO3− exchanger proteins of the SLC26 family, Down-Regulated in Adenoma (DRA, SLC26A3) and putative anion transporter-1 (PAT1, SLC26A6), mediate Cl− absorption." (PMID 33920650, 2021).
cystic fibrosis (2 papers, 2024). Autosomal recessive disorder caused by pathogenic variants in the CFTR gene (cystic fibrosis transmembrane conductance regulator), which encodes a chloride and bicarbonate channel expressed in epithelial cells, and follow the diagnosis criteria. "Based on the selective role of SLC26a6 in ileal fluid absorption in both WT and F508del mice, the authors speculate that the drug may be beneficial for the small intestinal obstructive problems in patients with cystic fibrosis." (PMID 39949394, 2024).
thyroid cancer (2 papers, 2023). "Compared with normal thyroid tissue, 7 CRGs were more highly expressed in thyroid cancer, namely BUB1 (P<0.001), RPL3 (P<0.001), TTK (P<0.001), GINS2 (P<0.001), SLC26A6 (P<0.001), CDKN2A (P<0.001) and ZNHIT2 (P<0.001)." (PMID 37745716, 2023).
breast carcinoma (1 paper, 2015). "There is a report of a single in-frame expressed fusion gene resulting from a chromosomal translocation in breast cancer between PRKAR2A and SLC26A6, which encodes an anion transporter, but the oncogenetic significance of this event has not been determined." (PMID 26608815, 2015).
chronic pancreatitis (1 paper, 2020). A chronic inflammatory process causing damage and fibrosis of the pancreatic parenchyma. "Therefore, SLC26A6 is a reasonable candidate for a chronic pancreatitis susceptibility gene." (PMID 33553213, 2020).
colorectal cancer (1 paper, 2014). A primary or metastatic malignant neoplasm that affects the colon or rectum. "Although the remaining 7 genes (PKD1, FAM38A, WDR81, TMEM136, SLC36A1, SLC26A6, IGFLR1) are mutated in >10% of the colorectal cancer cell lines, literature searches did not reveal evidence of the functional role or therapeutic potential of these genes in colorectal cancer." (PMID 25193853, 2014).
duodenal ulcer (1 paper, 2018). An ulcer in the duodenal wall. "We previously showed that H. pylori infection downregulated the expression and functional activity of duodenal mucosal CFTR and SLC26A6, which contributes to the development of duodenal ulcer." (PMID 30119655, 2018). "H. pylori infection downregulates duodenal epithelial cellular CFTR and SLC26A6 expressions through TGFβ-mediated P38 MAPK signaling pathway, which contributes to further elucidating the pathogenesis of H. pylori-associated duodenal ulcer." (PMID 30119655, 2018).
Hodgkins lymphoma (1 paper, 2018). A heterogeneous group of malignant lymphoid neoplasms of B-cell origin characterized histologically by the presence of Hodgkin and Reed-Sternberg (HRS) cells in the vast majority of cases. "Expression of FAM107A and SLC26A6 was low or absent in HRS cell lines and in HRS cells in Hodgkin lymphoma." (PMID 29755658, 2018). "Expression of FAM107A and SLC26A6 was low or absent in Hodgkin Reed-Sternberg (HRS) cell lines and in HRS cells in Hodgkin lymphoma tissue." (PMID 29755658, 2018).
ischemia (1 paper, 2025). A hypoperfusion of the BLOOD through an organ or tissue caused by a PATHOLOGIC CONSTRICTION or obstruction of its BLOOD VESSELS, or an absence of BLOOD CIRCULATION. "In the current study, we directly demonstrated that ablation of Slc26a6 reduced acid loading and increased pHi in cardiomyocytes and in ex vivo hearts, while the fall of cardiac pHi in Slc26a6−/− mice during ischemia may be ameliorated compared to WT mice." (PMID 41462888, 2025).
lentivirus infection (1 paper, 2018). Virus diseases caused by the Lentivirus genus. "The rate of stone formation and urinary oxalate concentration in rats with lv-Slc26a6 (Slc26a6 group) increased remarkably, whereas the rate in those with siRNA-Slc26a6 (siRNA group) decreased after lentivirus infection." (PMID 30002986, 2018).
renal tuberculosis (1 paper, 2018). Infection of the kidney due to mycobacteria. "Tissue samples were collected from patients with renal stones (stone former group) and patients suffering from renal tuberculosis or tumors (control group) to reveal the role of renal SLC26A6 in stone formers." (PMID 30002986, 2018).
cancer (8 papers, 2014 to 2024). A tumor composed of atypical neoplastic, often pleomorphic cells that invade other tissues. "Solute carrier family 26 member 6 (SLC26A6) exhibits overexpression in human HCC and is associated with various cancer-related pathways." (PMID 38534987, 2024). "The expression of SLC26A6 is up-regulated or remains the same in 11 of the 14 cancer types except for COAD, KIRC, and KIRP." (PMID 31071451, 2019). "Among other genes that were clustered with STS were several genes with ubiquitous expression in the normal tissues and documented overexpression in cancers: SLC26A6, TOMM40L, AKR1B1, NDRG2 and DGAT1 (based on TCGA data)." (PMID 29088719, 2017). "Firstly, the mRNA expression levels of most of the SLC4 and SLC26 family members differ widely between normal and cancer tissue, with a clear trend toward upregulation of SLC4A3, SLC4A7, and SLC26A6, and downregulation of SLC4A1 in cancer compared to normal tissue." (PMID 24795638, 2014).
infection (4 papers, 2018 to 2023). The state of being infected such as from the introduction of a foreign agent such as serum, vaccine, antigenic substance or organism. "Western blot and IHC analyses were used after successful lv-Slc26a6 and siRNA-Slc26a6 infection to demonstrate the variation in the expression of Slc26a6 in the kidneys and duodenum of rats." (PMID 30002986, 2018). "Furthermore, infection of lentivirus with Slc26a6 sequence and lentivirus with siRNA anti-Slc26a6 into the kidneys of rats was achieved." (PMID 30002986, 2018). "After infection for 2 weeks, an IHC assay was performed, and the results indicate that the expression of Slc26a6 decreased significantly in the kidney but was not altered in the duodenum." (PMID 30405874, 2018).
SLC26A6 also shares sentences with these, for which no sentence is quoted: Hypercalciuria (2 papers); primary hyperoxaluria (2); tumor (2); Arrhythmia (1); chronic hepatitis B (1); colorectal tumors (1); dysplasia (1); hyperglycaemia (1); Hyperkalemia (1); Hypertension (1); Infertility (1); inflammation (1); lung carcinoma (1); male infertility (1); myocardial ischemia (1); Pancreatic Diseases (1); primary hyperoxaluria type 2 (1); primary hyperoxaluria type 3 (1); Salmonella Infections (1); skeletal dysplasia (1); spermatocele (1); type 2 diabetes mellitus (1).